FOXM1 (forkhead box M1)
Diseases named in the same sentence as FOXM1 in open-access papers (continued):
Sharing a sentence is not in itself a finding about the gene and the disease.
breast cancer (continued). "Moreover, suppression of FOXM1 was shown to reduce breast cancer growth in vitro and in vivo." (PMID 33311446, 2020). "Regarding FOXM1, this transcription factor is a master regulator in cancer that is regulated by E2F1, and its overexpression is associated with an increased stem-like cell population and invasiveness in breast cancer, which is consistent with the C2 class being more dedifferentiated." (PMID 33396205, 2020). "Furthermore, we examined whether the levels of FOXO3a, FOXM1, SOX2, and DNMT1 were associated with the survival of patients with breast cancer." (PMID 31296961, 2020). "Forkhead box M1 (FOXM1), a member of the Forkhead box transcription factor family, is an oncogenic transcription factor, and its overexpression is associated with poor prognosis in several types of human cancers, such as pancreatic cancer, breast cancer, and lung cancer." (PMID 33053721, 2020). "(2015) showed that FOXM1 could target BIRC5 to modulate breast cancer survival and chemoresistance." (PMID 31579605, 2019). "Moreover, the overexpression of FOXM1 in breast cancer can interact with Smad3/Smad4 and inhibit the binding of TIF1γ to Smad4 to prevent its ubiquitination, which can attenuate the inhibitory effects of TIF1γ on TGF-β signaling to promote the metastasis of breast cancer." (PMID 31632911, 2019). "miR-802 has in several previous reports been described to act as a tumor suppressor; in breast cancer miR-802 was found down regulated, and in vivo and in vitro upregulation of miR-802 showed to suppress the cancer growth by down regulation of the oncogene FoxM1." (PMID 30475821, 2018). "In addition, recent genome-wide mapping of FOXM1 binding by chromatin immunoprecipitation with massively parallel DNA sequencing (ChIP-seq) analysis reveals the co-binding of FOXM1 with ERα in breast cancer cells, suggesting that FOXM1 is a common co-factor of ERα." (PMID 29180117, 2018). "Notably, BIRC5 and FOXM1 expression was also reduced in taxane-treated breast cancer patients, and FOXM1 expression was upregulated in most of the PTXR TNBC cell lines consistent with its established role in drug resistance to genotoxic agents, such as taxane and epirubicin." (PMID 28187446, 2017). "Furthermore, in breast cancer FOXM1 and HER2 expression is tightly correlated." (PMID 28388586, 2017). "We think that under conditions of FoxM1 over-expression there is a gain-of-function for Rb (and Rb family proteins) in which it participates in development/maintenance of poorly differentiated breast cancer cells by inhibiting expression of differentiation genes, such as GATA3 and FoxA1." (PMID 28387346, 2017). "Interestingly, our gene promoter and ChIP analyses reveal that this FHRE is located downstream of the most 5'-transcription start site, within the first non-coding exon, suggesting FOXM1 drives the transcription of KIF20A from this alternative promoter region in breast cancer cells." (PMID 25961928, 2016). "Moreover, PDGF/AKT pathway upregulates the expression of FoxM1 in breast cancer cells." (PMID 25869208, 2015). "Thus, high FOXM1 mRNA or protein confers a worse prognosis in ER+ breast cancers." (PMID 25213081, 2014). "We also mapped genome-wide FOXM1, extracellular signal-regulated kinase 2 and ERα binding events by chromatin immunoprecipitation followed by high-throughput sequencing (ChIP-seq) in hormone-sensitive and resistant breast cancer cells after tamoxifen treatment." (PMID 25213081, 2014). "Thus, whether FOXM1 is a downstream signaling target of casticin in breast cancer cells was investigated." (PMID 24765206, 2014). "Importantly, FOXM1 expression has been inversely correlated with poor prognosis in patients with oral squamous cell carcinoma, glioblastoma, breast cancer, hepatocellular carcinoma, pulmonary squamous cell carcinoma, and colorectal cancer." (PMID 23087907, 2012). "Therefore inhibition of FOXM1 expression could represent a new target in the therapeutic treatment of breast cancer." (PMID 18254960, 2008).
breast cancer (continued). "The overexpression of FOXM1 tends to transactive many oncogenes, which promote the proliferation, EMT, and metastasis of breast cancer." (PMID 40003882, 2025). "Among these different FOXM1 inhibitors the most well studied ones are FDI-6 and NB compounds, and they have been extensively studied in breast cancer and to some extent in ovarian cancer and multiple myelomas." (PMID 40630538, 2025). "For instance, in HCC, cervical squamous cell carcinoma, and breast cancer, USP39 and FoxM1 exhibit a synergistic effect in driving malignant tumor progression." (PMID 40672756, 2025). "For example, in breast cancer research, YTHDF1 recognizes and binds to FOXM1 mRNA through m6A modification, thereby facilitating the translation process of FOXM1 and promoting metastasis." (PMID 39821576, 2025). "Thus, we speculate that coincident expression of FOXC2 and FOXM1 in basal-like breast cancer cells contributes to both the maintenance and self-renewal of carcinoma cells undergoing a partial EMT, thereby supporting the stemness and aggressiveness of the TNBC subtype." (PMID 40764669, 2025). "Several FOXM1 inhibitors, including thiostrepton and FDI-6, warrant investigation as potential targeted treatments for KPNA2-high HR+HER2- breast cancer patients." (PMID 40002266, 2025). "As FOXM1 confers breast cancer cells’ phenotype of epirubicin resistance by repairing DNA damage, RNF 168 degrades FOXM1 through ubiquitination with the help of RNF8." (PMID 40003882, 2025). "The FOXM1 directly binds to and regulates CCNB1/CCNB2 promoters for breast cancer cell cycle progression, while KPNA2 modulates this process through its effects on FOXM1 nuclear transport and retention." (PMID 40002266, 2025). "In particular, FOXC1, FOXM1, and FOXO3 can all interact with BRCA1 and regulate the genome stability of breast cancer cells." (PMID 40003882, 2025). "Forkhead box M1 (FoxM1) directly regulates STMN1 gene transcription to overexpress tSTMN1 and confer resistance to paclitaxel in SKBR3 breast cancer cells." (PMID 40723207, 2025). "Forkhead Box M1 (FOXM1) is an oncogenic transcription factor that is upregulated in many cancer types, including breast cancer, where it promotes tumorigenesis and disease progression." (PMID 39335162, 2024). "Another study about basal-like breast cancer reported that USP21 promoted the progression of the cell cycle and resistance to paclitaxel by regulating FOXM1 deubiquitination." (PMID 38906857, 2024). "In breast cancer datasets, we found significant upregulation of both centrosome clustering proteins KIFC1, AURKB, BIRC5, and CDCA8 and the oncogenes FOXM1, ATAD2, and E2F1 in tumor samples compared to normal samples." (PMID 39335162, 2024). "Of interest, we also find that FOXM1 inhibition can synergize with activators of ferroptosis to markedly enhance anticancer activities in ER-positive and triple-negative cells, suggesting that this synergy may be broadly applicable to different subtypes of breast cancer." (PMID 38980505, 2024). "DeePathNet was able to highlight known biomarkers when predicting breast cancer subtypes, including ESR1, ERBB2, and the FOXM1 network pathways." (PMID 39530738, 2024). "It directly targets FOXM1, inhibiting cell viability, proliferation, and cell cycle progression in MCF-7 breast cancer cells." (PMID 39594778, 2024). "Mechanistically, we found that CDCA5 promoted the binding of E2F transcription factor 1 (E2F1) to FOXM1 promoter, and Wnt/β-catenin signaling was required for CDCA5 induced development of breast cancer." (PMID 38978058, 2024). "By identifying and binding m6A-modified FOXM1 mRNA and speeding up FOXM1 translation, YTHDF1 aids in the spread of breast cancer." (PMID 39342406, 2024). "The YTHDF1/FOXM1 regulatory pathway contributes to metastasis and growth of breast cancer through regulating PKM2 to affect the glycolysis and progression of breast cancer." (PMID 38339157, 2024).
breast cancer (continued). "Accordingly, the authors discovered a synergistic activity of FOXM1 and AURKA inhibitors in vitro and in breast cancer mouse xenografts." (PMID 38398147, 2024). "FOXM1 interacts with SMAD3 and induces breast cancer metastasis by supporting the activation of TGF-β." (PMID 39594778, 2024). "FOXM1 is the top-ranked survival-related transcription factor in patients with TNBC, and it is more highly overexpressed in TNBC compared to all other breast cancer subtypes." (PMID 37370117, 2023). "Patients co‐expressing FOXM1, survivin, and nuclear XIAP had significantly worst OS in breast cancer." (PMID 37154878, 2023). "In breast cancer cell lines, active FOXO3 has been reported to displace FOXM1 from the VEGF promoter, thereby reducing VEGF gene expression." (PMID 37174744, 2023). "They inhibited the growth of several breast cancer cell lines with IC50 values as low as 0.5 μM, and they reduced intracellular FOXM1 protein levels." (PMID 37370117, 2023). "FOXM1 targets the X-lined prohibitor of the apoptosis gene (XIAP), and survivin can be a potential component for resistance in breast cancer patients." (PMID 37626655, 2023). "The transcription factor, FOXM1, has been demonstrated to effect breast cancer cell migration; and functional assays in MDA-MB-231 mesenchymal breast cancer cells implicate ACSL4 as possible mediator of the FOXM1 effect." (PMID 37306503, 2023). "To study the impact of FOXM1 inhibition on mitosis in MAD2-overexpressing cells (MAD2 OE), we generated doxycycline (Dox) inducible human MAD2-expressing breast cancer cell lines (MCF7, CAL51, MDA-MB-231, and MCF10A)." (PMID 37452072, 2023). "For the five identified potential oncomiRs, miR-193a-3p promoted tumor progression by targeting GRB7, ERK1/2, and FOXM1 signaling pathways and PTP1B in HER2-positive breast cancer cells." (PMID 37508580, 2023). "We also noticed that, while FoxM1 expression fully rescued integrin b1 expression both in USP22-null 4T1 and TN1 breast cancer cells, but their sphere and colony formation were only partially restored by FoxM1 re-expression." (PMID 37398311, 2023). "In this study, we investigated the activity pattern of the FOXM1 and PPARA pathways in both TCGA breast tumor patient and breast cancer cell line data." (PMID 36424525, 2023). "In breast cancer, there is evidence that MEK-activated FOXM1 mediates resistance to lapatinib, a dual EGFR/HER2 tyrosine kinase inhibitor." (PMID 37686402, 2023). "Similar to our observation from USP22 CRISPR KO studies, treatment of breast cancer cells 4T1 and TN1 significantly inhibited both integrin b1 and FoxM1 expression." (PMID 37398311, 2023). "FOXM1 is a transcriptional regulator of NBS1 and facilitates double-strand break repair in breast cancer cells." (PMID 37025658, 2023). "Our previous studies demonstrated that the FOXM1 pathway is upregulated and the PPARA pathway downregulated in breast cancer (BC), and especially in the triple negative breast cancer (TNBC) subtype." (PMID 36424525, 2023). "E2F1 and c-Myc are overexpressed in basal breast cancers from NHB women, FoxM1 in Her2 + breast cancers from NHW women, FoxM1, E2F1 and E2F2 in Luminal A breast cancers from NHB women." (PMID 36494865, 2022). "FOXM1 deubiquitinated by USP21 modulates cell cycle and paclitaxel sensitivity of basal-like breast cancer cells." (PMID 35799265, 2022). "In breast cancer, HMGA1, EGF and TGFβ signaling pathways, HIF-1α all promoted EMT by upregulating FOXM1." (PMID 35197112, 2022). "Through recognizing and binding to the m6A-modified mRNA of FOXM1, YTHDF1 accelerated the translation process of FOXM1 and promoted breast cancer metastasis." (PMID 35197112, 2022). "Subsequently, CCK-8 assay, transwell, and wound healing assay were performed on breast cancer cells with sh-NC, sh-YTHDF1#2 or sh-YTHDF1#2 + FOXM1, respectively." (PMID 35197112, 2022).
breast cancer (continued). "Compared with HER2+ and HR+ breast cancers, FOXA1 was lowly expressed in TBNC, while FOXC1, FOXK2, and FOXM1 were highly expressed." (PMID 36292640, 2022). "MiR-8073 binds to at least five mRNAs (FOXM1, MBD3, CCND1, KLK10, and CASP2) in various cancers such as colon, pancreatic, and breast cancer in vitro and determines the gene and protein expression levels of these five targets." (PMID 35163589, 2022). "Based on the prior experimental results, we focus on the effect of FOXM1-PROTAC on the growth of Hepatoma cells and Breast cancer cells." (PMID 36171633, 2022). "In breast cancer, eight winning TFs (ZBTB16, KLF2, KLF4, NR2F1, EGR1, FOSB, EPAS1, and GPRASP1) can form a coregulatory network, and three other winning TFs (MYBL2, FOXM1, and TAL1) can form another coregulatory network." (PMID 36101460, 2022). "FOXM1 and E2F1 are also upregulated in various types of cancers, such as hepatocellular carcinoma, myeloma, colon cancer, breast cancer, and lung cancer." (PMID 35835838, 2022). "They concluded that blockade of the Wnt3a/FOXM1/β-catenin axis and activation of GSK-3β is essential for inducing apoptosis in breast cancer cells." (PMID 35744950, 2022). "In breast cancer, reducing intracellular O-GlcNAcation by inhibiting OGT attenuates the expression of the transcription factor FoxM1, further resulting in the downregulation of downstream target genes and inhibiting tumorigenesis." (PMID 36275679, 2022). "Similar to the findings in breast cancer cells, the co-IP assay demonstrated that ZMYND8 and FOXM1 interacted with each other at the endogenous level in ccRCC cells." (PMID 33593912, 2021). "In the breast cancer tissues, the strongest correlations were reported between FOXM1/ZNF337.AS1 and FOXM1/RAMP2.AS1 pairs (r = 0.51, P value = 4.79E−5 and r = 0.51, P value = 6.39E−5, respectively)." (PMID 34094972, 2021). "In the breast cancer tissues, the most strong correlations were reported between FOXM1/ZNF337.AS1 and FOXM1/RAMP2.AS1 pairs (r = 0.51, P value = 4.79E−5 and r = 0.51, P value = 6.39E−5, respectively)." (PMID 34094972, 2021). "In breast cancer cell lines, ERα drives cell proliferation by activating expression of proliferative genes, including CCND1, MYC, E2Fs and FOXM1." (PMID 34831189, 2021). "In breast cancer stem cells, nuclear AURKA is recruited by FOXM1 and binds to the FOXM1 promoter to transactivate its expression, while FOXM1 activates AURKA expression at the transcriptional level in a similar manner." (PMID 33451333, 2021). "FOXM1 is an important regulator of the mitogenic functions of ERα in breast tumor cells, and increased expression of FOXM1 subsequently might contribute to ERα+ breast cancer initiation and progression as FOXM1 triggers cell cycle progression and circumvents induction of senescence." (PMID 34831091, 2021). "Consistently, we found that FOXM1 was positively correlated with RNF26 in multiple types of malignant tumors, including bladder cancer, colon cancer, cervical cancer, breast cancer, prostate cancer, pancreatic cancer, liver cancer, and gastric cancer." (PMID 34650035, 2021). "In esophageal cancer, FOXM1 has been related to cell growth, proliferation, and metastasis and plays a key role in both PTX resistance in breast cancer and ovarian cancer." (PMID 34768915, 2021). "For example, in basal breast cancer, which has robust molecular similarity to HGSC, the DUB USP21 deubiquitinates and stabilizes FOXM1 in vitro and in vivo." (PMID 34205406, 2021). "Interrogation of CCLE database revealed a positive correlation of FZD5 with FOXM1, BRCA1, and BIRC5, several key factors related to cell cycle, DNA replication, DNA damage repair, and survival, in a total of 57 breast cancer cell lines." (PMID 33311446, 2020). "Hierarchical clustering of NCS‐1 and breast cancer molecular markers showed a positive correlation with basal and proliferative markers, such as KRT5, 14 and 17, CDH3, FOXC1, FOXM1, EGFR, and MKI67." (PMID 31647602, 2020).
breast cancer (continued). "Taken together, these findings indicated that dysregulated FOXO3a/FOXM1/SOX2/DNMT1 signaling plays a critical role in disease progression and is a valuable biomarker in breast cancer." (PMID 31296961, 2020). "Next, we analyzed the clinicopathological implication of FOXO3a, FOXM1, SOX2, and DNMT1 levels in breast cancer patients." (PMID 31296961, 2020). "We found that the combination of low FOXO3a expression and high FOXM1, SOX2, and DNMT1 expression was a strong predictor of shorter survival in breast cancer patients." (PMID 31296961, 2020). "Ursolic acid promoted apoptotic cell death in human breast cancer MCF-7 cells by Bcl-2 downregulation and suppressing the expression of transcription factor FoxM1, while in MDA-MB-231 cells via mitochondrial death and extrinsic death receptor pathway." (PMID 33138135, 2020). "FOXM1 and FOXO3A are decisive for ERα regulation in normal tissues, as well as during ER+ breast cancer initiation, progression, and the development of drug resistance." (PMID 32967092, 2020). "In the current study, we found that DNMT1-mediated FOXO3a promoter hypermethylation leads to downregulation of FOXO3a expression in breast cancer, and FOXO3a suppresses BCSC properties and tumorigenicity via inhibition of FOXM1/SOX2 signaling." (PMID 31296961, 2020). "As for the various molecular typing groups, low FOXO3a expression, or high expression of FOXM1, SOX2, and DNMT1 was relevant to shorter survival in ERα+ breast cancer patients." (PMID 31296961, 2020). "Taken together, our findings have clinical implications for breast cancer and possibly other cancers where PI3K/FOXM1 signaling pathways are active." (PMID 32976773, 2020). "Apart from breast cancer cells, BA was reported to suppress the cell cycle progression and proliferation of prostate cancer cells through the CDK6/FOXM1 axis." (PMID 32625089, 2020). "Collectively, our findings suggest an important role of the DNMT1/FOXO3a/FOXM1/SOX2 pathway in regulating BCSCs properties, suggesting potential therapeutic targets for breast cancer." (PMID 31296961, 2020). "A recent analysis of highly aneuploidy breast cancers in TCGA found overexpression of three transcriptional regulators, E2F1, MYBL2, and FOXM1." (PMID 32380981, 2020). "We next analyzed the correlation of FOXO3a, FOXM1, SOX2, and DNMT1 expression to the prognosis of breast cancer patients with lymph node metastasis status." (PMID 31296961, 2020). "PVT1 promotes cell progression, growth, invasion, and acquisition of stem cell-like properties by stabilizing FOXM1 and NOP2 proteins in breast cancer and hepatocellular carcinoma, respectively." (PMID 30809433, 2019). "(d-f) Kaplan Meier curves of RFS in a cohort of breast cancer patients stratified by HMGA1 (d), FOXM1 (e) and VEGFA (f) expression." (PMID 31311575, 2019). "In contrast, ECs incubated with conditioned medium from breast cancer cells silenced for HMGA1 and FOXM1 formed aggregates losing the capillary-like structures." (PMID 31311575, 2019). "In another previous study, we identified the same upstream effectors (ERBB2, RABL6, FOXM1 and MITF) to be the most effected by palbociclib treatment in the MDA-MB-231 breast cancer cells, reducing colony formation, cell migration and viability." (PMID 31835892, 2019). "This study reveals FOXM1 as a crucial interactor of HMGA1 and proves that their cooperative action supports breast cancer aggressiveness, by promoting tumor angiogenesis." (PMID 31311575, 2019). "Our results propose that PMLIV overexpression inhibits the proliferation of breast cancer cells by concurrently regulating the oncogenic transcription factor FOXM1 and the tumor suppressor FOXO3 that acts upstream of FOXM1." (PMID 30927552, 2019). "For all the parameters analyzed we found that breast cancer cells silenced for HMGA1 and FOXM1 reduced these parameters and, moreover, the concomitant silencing of the two factors restored normal conditions." (PMID 31311575, 2019).